CD163 (CD163 molecule)
Diseases named in the same sentence as CD163 in open-access papers (continued):
Sharing a sentence is not in itself a finding about the gene and the disease.
ovarian carcinoma (continued). "Indeed, CD68 and CD163 are both used to identify macrophages in tissue sections, but while CD68 is commonly used as a pan-macrophage marker, CD163 is regarded as a highly specific marker for M2-polarized macrophages in several human tumors, including ovarian cancer." (PMID 27462782, 2016). "To further prove the relationship between ALKBH5 and M2 macrophage markers in TME of ovarian cancer, we found that ALKBH5 positively correlated with M2 macrophage markers IL-10 and CD163 through Pearson analysis in ovarian cancer related dataset GSE158739." (PMID 38637813, 2024). "Embryonically derived resident macrophages (Tim‐4, CD163, and LYVE‐1 in peritoneal fluid, omentum, and peritoneum, respectively) can intraperitoneally promote ovarian cancer progression in mice." (PMID 39494816, 2024). "It has been demonstrated that the protumoral phenotype of TAMs can be mitigated by suppressing the expression of M2 phenotype markers, CD163 and CD209, in ovarian cancer A2780 cells." (PMID 38970121, 2024). "Ovarian cancer stem cells and macrophages grown together in spheroids result in increased CD206, CD163, and IL-10 expression, as well as WNT signaling pathway activity, compared with ovarian cancer cells grown in isolation." (PMID 37545408, 2023). "A retrospective study analyzing patients with stage III-IV ovarian cancer utilized CD68 and CD163 as M1 and M2 macrophage markers, respectively, to analyze the expression of TAMs within tumor samples." (PMID 35565348, 2022). "CD163 and CD206 have been suggested to be highly expressed on TAMs in ovarian carcinoma and can be used to predict its recurrence." (PMID 35842650, 2022). "HGSOC cells can recruit CD163+ TAMs through the release of periostin (POSTN), which is an ECM protein found to be elevated in ovarian cancer ascites." (PMID 35574025, 2022). "IHC analysis of 110 Chinese patients with stages III–IV epithelial ovarian cancer revealed that PFS and OS rates were higher in the low-CD163 expression group than in the high-CD163 expression group." (PMID 33194645, 2020). "CD163 and CD206/MRC1, which are strongly expressed on TAMs, are receptors for immunosuppressive molecules and predict the early recurrence of ovarian cancer." (PMID 32774171, 2020). "We went back to the analysis of TCGA datasets of human GBM and ovarian cancer and observed a significantly positive correlation between LIF and CCL2, CD163, and CD206 in both tumor types." (PMID 31186412, 2019). "Consistent with their tumor-promoting functions, TAM expressing high levels of the scavenger receptor CD163 and the mannose receptor CD206/MRC1 are immunosuppressive and predictive of an early relapse of ovarian carcinoma after first-line therapy (13, –15)." (PMID 29141914, 2018). "CD163 and MRC1 mRNA expression also correlated with the ascites levels of IL-10, which is prognostic of a short RFS of ovarian cancer." (PMID 29141914, 2018). "Recent studies examining markers of both M1 (HLA-DR, iNOS) and M2-polarization (CD163, VEGF) in ovarian cancer patients have demonstrated that an increased M1/M2 ratio was associated with improved patient survival." (PMID 24936477, 2014). "Some studies had found that ETS1 exosomes secreted by ovarian cancer cells induce the polarization of M2 macrophages, which overexpress CD163, IL-10, CCL2, CXCL5 and other immunosuppressive factors, and significantly stimulate the migration of ovarian cancer cells." (PMID 39539540, 2024). "In fact, the genetic and pharmacological depletion of CD163+Tim4+ macrophages and not MDMs regressed the metastatic spread of ovarian cancer." (PMID 38411356, 2024). "Studies analyzing the association between TAM infiltrates and prognosis have used various measures (i.e. CD163, CD68, M1/M2 ratio) and a meta-analysis in ovarian cancer (histologies combined) found that only the M1/M2 ratio was significant for both overall and progression free survival." (PMID 36368129, 2023).
ovarian carcinoma (continued). "Importantly, recent single cell RNA sequence data confirmed expression of CD16 (FCGR3A), CD206 (MRC1), CD163, and CRIg (VSIG4) in macrophages from both peritoneal fluid at steady state and ovarian cancer ascites." (PMID 37180125, 2023). "CD163 and CD206 function as immunosuppressive receptor molecules, and their expression usually indicates early recurrence and decreased relapse-free survival (RFS) times in patients with ovarian cancer." (PMID 35842650, 2022). "In addition, deoxyschizandrin was found to inhibit the expression of the M2 phenotype markers CD163 and CD209 in TAMs, macrophages stimulated by the ovarian cancer cells." (PMID 29342940, 2018). "However, siNOS2 treatment significantly decreased the percentage of CD163-positive cells in both siPDLIM2-transfected OVCAR-3 and Caov-3 ovarian cancer cell xenografts." (PMID 26593252, 2016). "Thus, in ovarian cancer, CD163 is not strictly indicative of M2 polarization but is a marker of a more nuanced macrophage phenotype linked to disease progression and immune modulation." (PMID 40330466, 2025). "Collectively, these findings clearly demonstrate that CD163+ TIM4+ macrophages in the omentum represent a distinct tissue-specific cellular subset crucial for ovarian cancer metastasis, highlighting their potential as therapeutic targets or prognostic biomarkers for ovarian cancer." (PMID 41208978, 2025). "To test this hypothesis, we analyzed M1 macrophage markers, including CD80, CD32, and CD64, and M2 macrophage markers, including CD68, CD206, and CD163, in HERV-K119 env KO THP-1 cells and compared them with those in HERV-K119 env KO OVCAR3 ovarian cancer cells." (PMID 37958549, 2023). "Another study enrolled 108 patients with advanced stage ovarian cancer, showing that the progression-free survival (PFS) and overall survival (OS) rates were significantly higher in the group with low expression of CD163 (immunostained specimens) in comparison with the high-CD163 expression group." (PMID 32456078, 2020). "Indeed, CD68 and CD163 are both used to identify macrophages in tissue section, but while CD68 is commonly used as a pan-macrophage marker, CD163 is regarded as a highly specific marker for M2-polarized macrophages in several human tumors, including ovarian cancer." (PMID 26797759, 2016). "Of note, the ratio of CD163+/CD206+ TAMs to ovarian cancer cells was increased in omental metastatic tumors (p = 0.0234), and the ratio of CD86+ TAMs to ovarian cancer cells was not (p = 0.3777), indicating that the metastatic microenvironment skews CD163+/CD206+ TAM polarization." (PMID 39198883, 2024).
Obesity (77 papers, 2012 to 2026). Accumulation of substantial excess body fat. "In the lung tissue, NOD1 deficiency during obesity led to elevated neutrophil accumulation, increased myeloperoxidase activity, reduced CD163+ macrophages, and enhanced β‐galactosidase activity." (PMID 40616268, 2025). "Traditionally, it was believed that obesity and aging were associated with an increased presence of inflammatory (iNOS+) M1 macrophages and anti-inflammatory (CD163+) M2 macrophages, both known to stimulate fibrotic collagen deposition by stromal fibroblasts." (PMID 38956667, 2024). "Studies have shown that HFD-induced obesity leads to an increase in collagen deposition in AT, which is associated with a reduction in the number of CD163+ macrophages." (PMID 37241120, 2023). "Obesity has previously been linked to the accumulation of CD11c+ CD163+ macrophages in both visceral and subcutaneous AT." (PMID 37048092, 2023). "Macrophage activation assessed by soluble CD163 is associated with hepatic insulin resistance in patients with severe obesity and its improvement after Roux‐en‐Y gastric bypass and weight loss." (PMID 35040267, 2022). "Total number of CD163+ cells in AT is known to increase with obesity and has been associated with IR50." (PMID 34285301, 2021). "NAFLD is a common, chronic inflammatory liver disease associated with obesity and characterized by a pattern of steatosis associated with low-grade CD163-positive inflammation." (PMID 26646450, 2015). "Soluble CD163 (sCD163) is a novel marker linked to states of low-grade inflammation such as diabetes, obesity, liver disease, and atherosclerosis, all prevalent in subjects with Turner syndrome (TS) and Klinefelter syndrome (KS)." (PMID 24148221, 2013). "However, these same cells completely lost expression of the M2-associated Cd163 gene with the onset of obesity." (PMID 35618862, 2022). "However, expression of Cd163, another M2-like marker, is lost with the onset of obesity and the loss persists during WL and WC." (PMID 35618862, 2022). "TWEAK and CD163 have been linked to obesity and associated cardiovascular diseases in adults." (PMID 35898446, 2022). "Consistent with previous reports, obesity enhanced the proportion of Itgax+ (encoding CD11c) and Cd9+ ATMs (cluster 0) and Plac8+ monocytes (cluster 4) and reduced the proportion of Lyve1+ and Cd163+ ATMs (cluster 1) and Lyz1+ monocytes." (PMID 34676827, 2021). "Another biomarker, connecting low-grade inflammation and T2DM, is the soluble form of the haptoglobin-hemoglobin receptor CD163 (sCD163), with observational studies suggesting that individuals with obesity have increased concentrations of sCD163 putting them at higher risk for T2DM." (PMID 33028418, 2020). "Thus, the observed obesity-associated increase in CD163+ macrophages in the tumor-adjacent adipose tissue of TNBC patients may contribute to the worse prognosis of these patients." (PMID 39456610, 2024). "Consistently, in males with overweight/obesity and T2DM, VAT and VAT/SAT ratio were reported to be positively associated with CD163, a marker of macrophage activation." (PMID 41077621, 2026). "Increased adipose tissue inflammation in CKD patients is independent of obesity status but at the same time obesity-associated changes in fat mass in CKD patients also correlate with CRP levels and soluble CD163 levels, which is an activated macrophage marker." (PMID 37128293, 2023). "Collagen VI is involved in the regulation of adipocyte differentiation and inflammation, and alterations in collagen expression and the number of CD163+ macrophages in AT play a crucial role in the development of obesity-related metabolic dysfunction." (PMID 37241120, 2023). "For CD163, there was a significant effect of obesity (F = 73.79; p < 0.0001) and OEA-DS administration (F = 11.87; p = 0.0009), and a significant interaction effect of these factors (F = 5.548; p = 0.0209)." (PMID 37892420, 2023).
Obesity (continued). "Meanwhile, the activation of macrophages in patients with obesity is reflected in raised circulating levels of inflammatory mediators, such as cytokines and soluble CD163 (sCD163)." (PMID 36466916, 2022). "Regarding CD163, this cytokine is higher in adults with obesity, and known as a biomarker of insulin resistance." (PMID 35898446, 2022). "The aim of this study was to observe serum levels of TWEAK and CD163 in prepubertal children with obesity compared to lean, and to evaluate its changes after a 2-year intervention program in children with obesity." (PMID 35898446, 2022). "Serum levels of CD163 are higher in obesity and insulin resistance, being a strong predictor of type 2 diabetes in adults." (PMID 35898446, 2022). "Tumor Necrosis Factor Weak Inducer of Apoptosis (TWEAK) and Cluster of Differentiation 163 (CD163) are cytokines potentially involved in the pathogenesis of obesity." (PMID 35898446, 2022). "A significant decrease in pro-inflammatory macrophages markers (mRNA levels of iNOS (P < 0.05), CD68 (P < 0.05), CD163 (P < 0.05)) was found within the subcutaneous AT of our IR subjects with obesity." (PMID 33753887, 2021). "On the other hand, pregravid obesity was associated with up-regulation of immunoregulatory molecules such as AHR (1.44-fold), CD52 (1.21-fold), and CD163 (1.8-fold)." (PMID 34195568, 2021). "Obesity and T2DM were associated with increased CD68 marker expression (P<0.001) while CD11b and CD163 expression were significantly inhibited in T2DM (P<0.005)." (PMID 30356719, 2018). "CD163 is the macrophage scavenger receptor which takes up Hp–Hb complexes, but sCD163 levels increase with obesity and metabolic disorders." (PMID 30127325, 2018). "Soluble CD163 (sCD163) is the extracellular part of CD163 and it is found to be shed of the receptor during proinflammatory conditions and in obesity." (PMID 24741586, 2014). "CD 163, a glycosylated membrane protein expressed exclusively by cells of monocytic lineage (monocytes, macrophages), and its soluble form sCD163, have been extensively studied in the setting of inflammation as well as obesity and related co-morbidities." (PMID 24025484, 2013). "CD163, one of the hubgenes found this study, encodes a monocyte/macrophage specific receptor whose soluble form (sCD163) is elevated in T2D and obesity." (PMID 22383892, 2012). "Translational studies in humans will also be needed to confirm whether soluble M2 markers such as CD163 can serve as reliable biomarkers of exercise-induced immune adaptation in obesity." (PMID 41556049, 2026). "In CRC groups, patients with obesity exhibited higher CD163+ TAM expression." (PMID 41395618, 2025). "Multivariate regression confirmed this association in CRC (β = 16405.198, 95% CI: 11878.446 ~ 20931.949), suggesting that obesity-induced TME changes may contribute to CD163+ TAM enrichment and tumorigenesis." (PMID 41395618, 2025). "Obesity on the other hand seemed to be associated with changes in immune cell infiltration with increased intraepithelial CD8+ T-cells, especially in patients with T2DM and with increased stromal CD163+ M2 macrophages." (PMID 39685707, 2024). "An effect of obesity is only seen in increased intraepithelial CD163+ cells in benign histology." (PMID 39685707, 2024). "We observed higher CD163 levels in children with obesity compared to controls." (PMID 35898446, 2022). "Comparing cases and controls, CD163 levels were higher in children with obesity." (PMID 35898446, 2022). "TWEAK and CD163 seem to have a role in the pathogenesis of obesity in prepubertal children." (PMID 35898446, 2022). "Our findings show that TWEAK and CD163 may be involved in the pathogenesis of obesity in prepubertal children." (PMID 35898446, 2022). "In our study, CD163 serum levels were also higher in children with obesity compared to lean." (PMID 35898446, 2022).
Obesity (continued). "Moreover, obesity increased Ant2 expression in Itgax–, Lyve1+, and Cd163+ ATMs, although Ant2 expression was unchanged by LPS treatment in BMDMs." (PMID 34676827, 2021). "Furthermore, elevated levels of MIP-1α/CCL3 positively correlate with TNF-α and CD163 in fat tissues from individuals with obesity." (PMID 33050324, 2020). "In addition, CD163 encodes a monocyte/macrophage specific receptor whose soluble form (sCD163) is elevated in T2D and obesity." (PMID 22383892, 2012). "Muscle aging is associated with diabetes and obesity, and in the present study, we compared the expressions of the FMOD and MSTN genes and those of genes related to muscle aging (Atrogin 1, Glb1), diabetes (RAGE, CD163) and intracellular lipid accumulation (CD36, PPARγ) in vivo and in vitro." (PMID 34440852, 2021). "In conclusion, our data support a model in which human obesity leads to the elevated expression of IL-6R and IL-6 in the adipose tissue, with increased tissue expression of TNF-α, MCP-1, IP-10 and infiltration by CD11b+/CD163+ macrophages as the underlying features of meta-inflammation." (PMID 26200663, 2015). "Induced UCB-derived microglia-like cells (iMGL) expressed higher levels of activation markers CD163, CX3CR1, TMEM119, and HLA-DR but reduced phagocytic capacity with maternal pregravid obesity." (PMID 39872537, 2024). "Here, using a model of microglia derived from UCBMC in vitro (iMGL), we report an increase in the expression of activation markers (CD163, CX3CR1, TMEM119, HLA-DR) with pregravid obesity, while phagocytic capacity was reduced." (PMID 39872537, 2024). "Human ATMs in adipose tissue are thought to exhibit a mixed phenotype in obesity, characterized by the common expression of CD11c (M1), CD206, and CD163 (M2)." (PMID 37569635, 2023). "Our data, therefore, suggest a paradoxical effect of cytokines to stimulate the soluble CD163 level in OT2D; elevated circulating CD163 has been reported in obesity and T2D41." (PMID 33742062, 2021). "Next, we found that the increased TLR8 gene expression in the adipose tissues in obesity/T2D paralleled with enhanced expression of monocyte/macrophage markers such as CD68, CD11c, CD86, and CD163." (PMID 27980459, 2016). "CD163, CD206, and arginase-1 (Arg-1) act as makers of an alternative activation of monocytes/macrophages (M2, anti-inflammatory phenotype), and play a crucial role in chronic inflammation of obesity-related metabolic diseases." (PMID 36687421, 2022). "In addition, the investigation aimed to evaluate serum levels of TWEAK, CD163, and CD163/TWEAK ratio in prepubertal children with obesity compared to lean children." (PMID 35898446, 2022). "Quantitative amounts of CD163+ monocytes were not different between non-diabetic patient groups neither with nor without obesity." (PMID 36687421, 2022). "↑CD68 marker in obesity and in T2DM.↓CD11b, CD11c, CD163 and CD169 in T2DM patients↑TNFα, iNOS, IL-6, CD16, CD36, and CD206 in the T2DM Metformin restored TNFα, iNOS, IL-6, CD11c, CD36, CD169 and CD206 in T2DM patients to levels equivalent to those of lean volunteers." (PMID 34163481, 2021). "CD163 and CD206 expression on tissue MΦ has been used to distinguish an alternative activation state from classical activation in many human diseases like asthma, obesity and atherosclerosis." (PMID 24205083, 2013). "Additionally, regulatory genes such as CD163, AHR, and CD52 were increased with pregravid obesity." (PMID 34195568, 2021). "Furthermore, within the population of macrophages with high CD206 expression, there was higher expression of CD11b, CD11c, CD32, CD80, CD86, CD163, CD192, and HLA-DR in obesity, suggesting that these macrophages were activated and shared components of both classical M1 and M2 expression patterns." (PMID 30719456, 2019).
Obesity (continued). "Although we could not identify the underlying mechanism or the link among resistin, leptin, and CD163/CD68 expression levels, our data suggest that serum resistin levels and leptin levels have specific roles in the regulation of ATM in patients with modest obesity." (PMID 27101398, 2016).